HSPD1 (heat shock protein family D (Hsp60) member 1)
Diseases named in the same sentence as HSPD1 in open-access papers (continued):
Sharing a sentence is not in itself a finding about the gene and the disease.
HSPD1 also shares sentences with these, for which no sentence is quoted: tuberculosis (27 papers); autoimmune disease (26); Arthritis (16); periodontitis (13); bacterial infections (11); rheumatoid arthritis (10); Granuloma (9); hepatocellular carcinoma (7); co-infection (6); Lupus (6); Obesity (6); scrub typhus (6); Behcet disease (5); leprosy (5); Q fever (5); coronary artery disease (4); Hypertension (4); leptospirosis (4); schistosomiasis (4); spotted fever (4); anaplasmosis (3); Cardiovascular Disease (3); cervical cancer (3); Chlamydia infection (3); chlamydial infection (3); Crohn disease (3); endocarditis (3); endometrial cancer (3); endothelial dysfunction (3); experimental autoimmune encephalomyelitis (3).
A further 160 diseases each share a sentence with HSPD1 in 3 papers or fewer.